GPC3 (glypican 3)
Diseases named in the same sentence as GPC3 in open-access papers (continued):
Sharing a sentence is not in itself a finding about the gene and the disease.
fatty liver disease (2 papers, 2023 to 2025). A reversible condition wherein large vacuoles of triglyceride fat accumulate in liver cells via the process of steatosis. "When encountering nodules with multiple hepatic steatosis, if glypican-3 and heat shock protein 70 are negative, and CD34 does not show diffuse hepatic sinusoidal capillarization, this is an opportune moment to carefully evaluate the expression patterns of GS and CD34." (PMID 41366899, 2025).
Fever (2 papers, 2022). Body temperature elevated above the normal range. "In GPC3 vaccine therapy, there are reports of patients with tumor lysis syndrome after the second GPC3 peptide injection, which led to high fever, liver failure, and death." (PMID 35251989, 2022). "Shi and colleagues discussed results from two phase I studies that enrolled 13 patients with advanced HCC treated with GPC3-CAR T cells; preliminary data showed 2 partial responses, 1-year OS rate of 42%, and most common toxicities included pyrexia, lymphopenia, and cytokine release syndrome." (PMID 35433430, 2022).
gestational trophoblastic neoplasm (2 papers, 2010 to 2013). A diverse group of pregnancy-related tumors characterized by excessive proliferation of trophoblasts. "As the β-HCG level was not elevated in 20% of patients with a PSTT or ETT, glypican 3 was recently suggested to be a potential serum tumor marker of gestational trophoblastic neoplasms." (PMID 23688193, 2013). "Although GPC3 expression has been studied in non-neoplastic placental tissue, its presence in gestational trophoblastic diseases has not been previously explored." (PMID 20868507, 2010).
gynecological cancer (2 papers, 2010 to 2014). "In this case, immunohistochemistry was positive/negative for CK7/CK20 and negative for glypican-3, suggesting that this tumor could be metastatic tissue from gynecological cancer." (PMID 25530894, 2014).
hepatitis B (2 papers, 2017 to 2022). "The expression levels of several exosomal proteins, including carcinoembryonic antigen (CEA), GPC-3, PD-L1 and HER2, have been used in combination to identify healthy individuals, hepatitis B patients, and HCC patients." (PMID 36167539, 2022).
metastatic melanoma (2 papers, 2018 to 2022). A melanoma that has spread from its primary site to another anatomic site. "Therefore, although the main purpose of this study was to develop a novel siRNA carrier, we also proved that GPC3 could be a target for therapies against metastatic melanoma." (PMID 35456649, 2022).
mixed germ cell tumor (2 papers, 2012 to 2020). A malignant germ cell tumor characterized by the presence of at least two different germ cell components. "Because of its selective expression in YST of mixed germ cell tumor, GPC3 can be used as a marker to differentiate YST among other germ cell elements." (PMID 22848863, 2012).
papillary carcinoma (2 papers, 2010 to 2021). A malignant epithelial neoplasm characterized by a papillary growth pattern. "When expression of GPC3 was investigated in 69 cases of papillary carcinomas according to their clinical background, it was found to be expressed at an early stage." (PMID 20652009, 2010).
rectal cancer (2 papers, 2021 to 2023). A primary or metastatic malignant neoplasm that affects the rectum. "miR-96-5p induced radioresistance is upregulated in rectal cancer cells through the inhibition of GPC3 and abnormal triggering of the canonical Wnt signaling pathway." (PMID 36900159, 2023). "MiR-96-5p also reportedly induces radioresistance in rectal cancer cells by inhibiting glypican 3 (GPC3) and abnormally triggering the canonical Wnt signaling pathway." (PMID 36900159, 2023). "After the over-expression of GPC3 gene in HR-8348 cells, we found that the radiation sensitivity of rectal cancer cells was significantly increased, which was consistent with our results of miRNA-96-5p knockdown." (PMID 34458143, 2021). "The down-regulated expression of GPC3 gene directly regulated by miRNA-96-5p might be one of the reasons for irradiation resistance of rectal cancer cells, and this effect may be related to the activity changes of Wnt/β-catenin signal transduction pathway." (PMID 34458143, 2021). "Therefore, we speculated that there may be a regulatory system of miRNA-96-5P/GPC3/Wnt/β-catenin in rectal cancer cells." (PMID 34458143, 2021).
salivary gland tumors (2 papers, 2020 to 2024). "There is another study which demonstrates the possible role of GPC3 in malignant transformation of salivary gland tumors." (PMID 32582830, 2020). "Higher expression of GPC3 in malignant salivary gland tumors in comparison with benign salivary gland tumors showed in this investigation." (PMID 32582830, 2020). "The authors suggest using GPC-3 as a target for potentially targeted salivary gland tumor therapy." (PMID 39684268, 2024).
sarcopenia (2 papers, 2023 to 2024). Progressive decline in muscle mass due to aging which results in decreased functional capacity of muscles. "Six biomarkers—BTG2, FOXO3, AQP9, GPC3, CYCS, and SCN1B—were identified alongside a diagnostic model that offers a novel approach for early diagnosis of sarcopenia." (PMID 39777262, 2024). "The highlight of our study is the identification of six potential diagnostic markers for sarcopenia: BTG2, FOXO3, AQP9, SCN1B, CYCS, and GPC3." (PMID 39777262, 2024). "All these AI tasks (detection, segmentation, classification) would work as automatic processing steps that could impact survival, such as early detection, sarcopenia, and the presence of imaging markers (MVI, grading, GPC3, CK19) are essential for prediction outcomes." (PMID 37175054, 2023).
signet ring cell carcinoma (2 papers, 2016 to 2019). A usually aggressive, poorly differentiated invasive adenocarcinoma characterized by the presence of malignant glandular cells in which the nucleus is pressed to one side by the presence of intracytoplasmic mucus. "The expression of GPC3 was much lower in signet ring cell carcinomas in comparison to other adenocarcinomas." (PMID 31100935, 2019). "Signet ring cell carcinoma, the subtype with the lower overall expression of GPC3 than adenocarcinoma, shows significantly higher levels of FoxM1 compared to adenocarcinoma (p=0.015)." (PMID 27259271, 2016). "Here, we report that Glypican-3 (GPC3) is absent in invasive tumors and metastatic lymph nodes, in particular in aggressive and highly disseminated signet ring cell carcinomas." (PMID 27259271, 2016).
teratoma (2 papers, 2023 to 2024). A non-seminomatous germ cell tumor characterized by the presence of various tissues which correspond to the different germinal layers (endoderm, mesoderm, and ectoderm). "Intriguingly, teratoma-1 showcased an expression signature reminiscent of immature teratomas, underscored by its expression of GPC3 - a marker previously associated with immature teratoma." (PMID 39528470, 2024).
testicular yolk sac tumor (2 papers, 2023). A non-seminomatous malignant germ cell tumor arising from the testis. "Glypican‐3 (GPC3) is highly expressed in testicular yolk sac tumor (TYST)." (PMID 37986544, 2023).
thyroid neoplasms (2 papers, 2023 to 2025). "Histologically, the left thyroid lobe biopsy of our patient presents negative markers for primary thyroid neoplasms (TTF-1 and TG) and positive markers for hepatitis-associated disease (AFP and GPC3), confirming the presence of poorly differentiated metastatic HCC." (PMID 40575170, 2025).
viral infection (2 papers, 2014 to 2023). "Stable HCC cell lines expressing shRNA against GPC3 or luciferase were successfully obtained by cell sorting with enhanced green fluorescent protein (EGFP) as a marker for viral infection." (PMID 24454751, 2014). "In the present work, NK cells were modified with the Gpc3 aptamer without viral infection." (PMID 37665421, 2023).
adenoma (1 paper, 2023). A neoplasm arising from the epithelium. "Beta-catenin, glutamine synthetase, glypican-3, and heat-shock protein 70 are promising markers to identify higher risk adenomas." (PMID 37427296, 2023).
adrenal carcinoma (1 paper, 2019). A carcinoma involving a adrenal gland. "In HE staining, the morphology of two tumors were slightly different; therefore, we evaluated two HCC markers (GPC3 and AFP) and two adrenal carcinoma markers (vimentin and Melan-A) via IHC staining." (PMID 31696344, 2019). "In adrenal carcinoma, GPC3 is not expressed, and the positivity rates of vimentin and Melan-A were 54% and 84%, respectively." (PMID 31696344, 2019).
adrenal tumor (1 paper, 2019). "Immunohistochemical staining revealed that both HCC cells and adrenal tumor cells were positive for HCC markers Glypican-3 and alpha-fetoprotein." (PMID 31696344, 2019). "HCC and adrenal tumor are both diffusely positive for Glypican-3 (GPC3)." (PMID 31696344, 2019).
Airway obstruction (1 paper, 2025). Obstruction of conducting airways of the lung. "GPC3 is the most expressed transcript in tracheobronchial epithelial cells, and the decrease in GPC3 transcript levels correlates with the severity of airway obstruction in chronic obstructive pulmonary disease (COPD) patients." (PMID 40422229, 2025).
aneurysm (1 paper, 2022). Bulging or ballooning in an area of an artery secondary to arterial wall weakening. "In our other dataset (GSE54083), we were surprised to find that the expression of CDH11, SPARC, FN1, and FSTL1 in unruptured aneurysms was significantly increased, while WNT11, PCDH9, and GPC3 expression levels were relatively low." (PMID 34997174, 2022). "It was found that the expression levels of CDH11, SPARC, FN1, and FSTL1 genes in unruptured aneurysms were higher than those in healthy samples, while the expression levels of WNT11, PCDH9, and GPC3 in unruptured aneurysms were lower than those in healthy samples." (PMID 34997174, 2022).
chronic hepatitis B (1 paper, 2023). "Researchers further validated in clinical samples that both EV GPC-3 and CEA could effectively discriminate HCC patients from chronic hepatitis B patients and healthy controls, indicating the enormous potential of these EV proteins as effective biomarkers for early diagnosis of HCC." (PMID 37006626, 2023).
chronic kidney disease (1 paper, 2025). Impairment of the renal function secondary to chronic kidney damage persisting for three or more months. "We identified the hub genes of CKD (Fn, Timp1, C3, Apoe, Trf, Fbn1, FGG, Penk, Ckap4, and Gpc3) through multiple bioinformatics analyses and successfully verified their expression in a mouse chronic kidney disease model." (PMID 40564035, 2025).
chronic pancreatitis (1 paper, 2024). A chronic inflammatory process causing damage and fibrosis of the pancreatic parenchyma. "For example, they note GPC3 staining in some areas of chronic pancreatitis and benign peritumoral tissues, suggesting that their staining protocol may be reacting non-specifically." (PMID 39598037, 2024).
cognitive deficits (1 paper, 2025). "Intellectual disability was universally present in individuals with variants in ZC4H2 (5/5), DYNC1H1 (4/4), TOR1A (2/2), KAT6B (1/1), GLDN (1/1), and GPC3 (1/1), signifying a strong association between these genes and cognitive deficits." (PMID 40443119, 2025).
colonic adenocarcinoma (1 paper, 2026). "CAED is a rare subtype of colonic adenocarcinoma characterized by increased AFP production and expression of at least one enteroblastic marker, including AFP, glypican 3, or SALL4." (PMID 41589237, 2026).
congenital diaphragmatic hernia (1 paper, 2011). A posterolateral defect of the diaphragm that allows passage of abdominal viscera into the thorax, leading to respiratory insufficiency and persistent pulmonary hypertension with high mortality. "Further compelling evidence for a critical role of HS in lung disease is the association in humans and mice of mutations in the HSPG, glypican-3, with lung hypoplasia and congenital diaphragmatic hernia (CDH), known as Simpson-Golabi-Behmel syndrome." (PMID 21672206, 2011).
diabetic cardiomyopathy (1 paper, 2016). Diabetic cardiomyopathy is a disorder of the heart muscle in people with diabetes. "Membrane proteoglycans Gpc3 and Sdc1 have not yet been demonstrated to play a role in the development of diabetic cardiomyopathy, however, increased expression of the heparan sulfate proteoglycans Gpc1 and Sdc4 has been shown to lead to diastolic dysfunction in streptozotocin-induced diabetic rats." (PMID 27496100, 2016).
dysgerminoma (1 paper, 2023). A malignant germ cell tumor characterized by the presence of a monotonous primitive germ cell population. "Tumor cells were positive for OCT3/4, SALL4, and CD117 and negative for CD30 and Glypican 3, leading to a dysgerminoma diagnosis (data not shown)." (PMID 37575996, 2023).
endometrial adenocarcinomas (1 paper, 2010). "Uterine tumors including one leiomyosarcoma, one leiomyoma and eleven endometrial adenocarcinomas were negative for GPC3." (PMID 20868507, 2010).
endometrioid adenocarcinoma (1 paper, 2025). An adenocarcinoma characterized by the presence of malignant glandular epithelial cells resembling endometrial cells. "A diagnosis of high-grade endometrioid adenocarcinoma with YST differentiation was rendered based on the morphologic features and immunopositivity for SALL-4, glypican-3, and AFP." (PMID 41510478, 2025).
epilepsy (1 paper, 2022). A brain disorder characterized by episodes of abnormally increased neuronal discharge resulting in transient episodes of sensory or motor neurological dysfunction, or psychic dysfunction. "Of the glypican family, GPC3 and GPC4 have been implicated in the development and progression of epilepsy." (PMID 36289737, 2022). "Indeed, the proposed mechanisms of action of GPC3 in tumorigenesis are also relevant in the development of epilepsy." (PMID 36289737, 2022).
esophageal adenocarcinoma (1 paper, 2019). A malignant tumor with glandular differentiation arising predominantly from Barrett mucosa in the lower third of the esophagus. "Here, we sought to investigate the diagnostic and prognostic value of the expression of glypican 3 (GPC3) on primary gastro-esophageal adenocarcinoma (GEA) tissue (tGPC3) and corresponding serum exosomes (eGPC3)." (PMID 31100935, 2019).
follicular carcinomas (1 paper, 2010). "Expression of GPC3 in follicular carcinomas was significantly higher than that of follicular adenomas (P < .0019)." (PMID 20652009, 2010).
gastrointestinal stromal tumor (1 paper, 2021). "A classifier developed using SVM was able to identify glypican 3-positive HCC; one that was based on RF effectively predicted the malignant potential of gastrointestinal stromal tumors; and an MLR-based classifier predicted coronavirus disease (COVID)-infected pulmonary lesions." (PMID 34476208, 2021).
invasive breast carcinoma (1 paper, 2022). A carcinoma that infiltrates the breast parenchyma. "GEPIA analysis for GPC3 mRNA expression showed that significantly low levels of GPC3 mRNA were found in invasive breast carcinoma compared to matched normal tissues." (PMID 36676710, 2022). "The results demonstrated that a significantly lower level of GPC3 expression was found in invasive breast carcinomas compared to matched normal tissues." (PMID 36676710, 2022). "Here, we investigated the expression of GPC3 at the mRNA level in the data of invasive breast carcinoma matched with normal tissue samples obtained from TCGA by GEPIA mRNA analysis." (PMID 36676710, 2022). "In other words, almost all of the invasive breast carcinoma samples in our cohort were negative for GPC3 protein expression." (PMID 36676710, 2022).
Jaundice (1 paper, 2023). Yellow pigmentation of the skin due to bilirubin, which in turn is the result of increased bilirubin concentration in the bloodstream. "While GPC3 expression was significantly higher in jaundice-free group." (PMID 36816373, 2023).
Keipert syndrome (1 paper, 2021). "Defects in glypicans, a group of heparan sulfate proteoglycans (HSPGs), can cause abnormal skull and skeletal dysplasia in both humans (Simpson–Golabi–Behmel syndrome: glypican 3, GPC3; Keipert syndrome: glypican 4, GPC4) and zebrafish (Knypek: Gpc4)." (PMID 34595172, 2021).
leiomyoma (1 paper, 2010). A well-circumscribed benign smooth muscle neoplasm characterized by the presence of spindle cells with cigar-shaped nuclei, interlacing fascicles, and a whorled pattern. "GPC3 was not expressed in uterine leiomyosarcoma and leiomyoma in the few cases we examined." (PMID 20868507, 2010).
mammary adenocarcinoma (1 paper, 2016). "In this regard, we previously showed that the ectopic expression of GPC3 in the LM3 murine mammary adenocarcinoma cell line was able to inhibit invasion and metastasis." (PMID 27507057, 2016). "In association, we have previously demonstrated that the re-expression of GPC3 induced a decrease in the apoptosis resistance acquired by the LM3 murine mammary adenocarcinoma cells." (PMID 27507057, 2016). "In the same way, we have previously reported that GPC3 re-expression reduced the ability of the LM3 murine mammary adenocarcinoma cells to invade the dermis and to form lung metastasis." (PMID 27507057, 2016).
mucinous carcinomas (1 paper, 2022). "All cases of Paget’s disease showed GPC3 expression, while 42.9% (six cases) of intraductal and 16.7% (one case) of mucinous carcinomas displayed GPC3 expression." (PMID 36676710, 2022).
oral squamous cell carcinoma (1 paper, 2020). "GPC3 was over expressed at protein level in oral squamous cell carcinoma, but its potential use for diagnostic and therapeutic purposes requires further investigation." (PMID 32582830, 2020). "The aim of the present study was to investigate GPC3 expression in the non-neoplastic oral epithelium and oral squamous cell carcinoma." (PMID 32582830, 2020).
osteoarthritis (1 paper, 2024). A noninflammatory degenerative joint disease occurring chiefly in older persons, characterized by degeneration of the articular cartilage, hypertrophy of bone at the margins and changes in the synovial membrane. "In the context of Osteoarthritis and Glypican 3, a recent study evaluated GPC3 levels in the synovial fluid of patients with knee OA compared to controls." (PMID 38786073, 2024).
ovarian clear cell adenocarcinoma (1 paper, 2024). A malignant glandular epithelial neoplasm characterized by the presence of clear and hobnail cells. "And overexpression of GPC3 may be related to the development and aggressive behavior of ovarian clear cell adenocarcinoma." (PMID 38824600, 2024).
ovarian epithelial tumor (1 paper, 2024). A benign, borderline, or malignant tumor that originates from the surface epithelium of the ovary. "These interesting findings about GPC3 have not been seen in other types of ovarian epithelial tumors." (PMID 38824600, 2024).
Paget disease (1 paper, 2022). A malignant neoplasm composed of large cells with large nuclei, prominent nucleoli, and abundant pale cytoplasm (Paget cells). "This is particularly exemplified by Paget’s disease and intraductal carcinomas overexpressing GPC3 in our study." (PMID 36676710, 2022). "Additionally, it is interesting to note that almost all GPC3-positive cases of Paget’s disease and intraductal carcinomas were positive for all hormone and HER2 receptors." (PMID 36676710, 2022).